AGL (amylo-alpha-1,6-glucosidase and 4-alpha-glucanotransferase)
Diseases named in the same sentence as AGL in open-access papers (continued):
Sharing a sentence is not in itself a finding about the gene and the disease.
bladder cancer (continued). "Similarly, amylo-α-1,6-glucosidase, 4-α-glucanotransferase (AGL), a key enzyme of glycogenolysis, was found to have an inhibitory effect on bladder cancer." (PMID 34136492, 2021). "Thus we conclude that inhibition of this pathway at various points can be beneficial for personalized treatment of bladder cancer patients with low AGL expression." (PMID 27595989, 2016). "Western blot analysis and Terminal deoxynucleotidyl transferase (TdT) dUTP Nick-End Labeling (TUNEL) assay was carried out to study cellular apoptosis with HAS2, CD44 and RHAMM loss in bladder cancer cells with and without AGL expression." (PMID 27595989, 2016). "Interestingly loss of either CD44 or RHAMM induces apoptosis in different low AGL expressing bladder cancer cell lines." (PMID 27595989, 2016). "Next we looked into cellular apoptotic pathway with loss of HAS2 in bladder cancer cells with and without AGL." (PMID 27595989, 2016). "However the role of HA receptors CD44 and Hyaluronan Mediated Motility Receptor (RHAMM) in regulating the growth of bladder cancer cells driven by loss of AGL has not been studied." (PMID 27595989, 2016). "We have previously established that loss of AGL drives aggressive bladder cancer growth via HAS2 mediated HA synthesis and provided preclinical evidence that targeting the HAS2/HA axis is possibly therapeutically beneficial for bladder cancer patients with low AGL expression." (PMID 27595989, 2016). "Clinicopathologic analysis revealed that high RHAMM mRNA expression is a marker of poor patient outcome in bladder cancer and patients with high RHAMM and low AGL tumor mRNA expression have poor survival." (PMID 27595989, 2016). "Treatment with superfluous amounts of LMW HA had little impact on CD44 and RHAMM expression of UMUC3 and T24T bladder cancer cells irrespective of AGL expression status." (PMID 27595989, 2016). "Interestingly loss of CD44 did not induce DR5 or apoptotic signaling in T24T bladder cancer cells with or without AGL expression." (PMID 27595989, 2016). "Interestingly loss of HAS2 does not reduce expression of CD44 and RHAMM in bladder cancer cells irrespective of AGL expression status." (PMID 27595989, 2016). "Interestingly when we knocked down HAS2 or treated with 4MU, UMUC3 and T24T bladder cancer cells +/− AGL expression had no change in their CD44 and RHAMM expression." (PMID 27595989, 2016). "Bladder cancer cells UMUC3 and T24T cells with (shCTL) and without (shAGL) AGL was used in this study." (PMID 27595989, 2016). "Lowering AGL enhanced tumour growth by increasing glycine synthesis through increased expression of serine hydroxymethyltransferase 2 (SHMT2), whilst depletion of the SHMT2 rescues the effects of tumour growth of bladder cancer cells without AGL." (PMID 26882899, 2016).
bladder tumor (5 papers, 2016 to 2024). "We have earlier shown that in bladder tumors, loss of AGL promotes rapid anchorage dependent and independent growth of cancer cells." (PMID 29682180, 2018). "The aim of the study was to identify if aggressive bladder tumor growth mediated by AGL loss depends on either CD44 or RHAMM or both." (PMID 27595989, 2016). "However in bladder tumors, loss of AGL profoundly increased anchorage independent growth and xenograft growth." (PMID 29682180, 2018). "Our previous study in the bladder tumor model indicated metabolic reprogramming and increased glucose uptake and glycolysis with AGL loss may play an important role in increasing HA synthesis." (PMID 29682180, 2018). "We have earlier shown that loss of AGL results in increased HAS2 expression and HA synthesis in bladder tumors." (PMID 29682180, 2018). "We have recently identified AGL as a suppressor of bladder tumor growth and established for the first time that AGL plays a role in cancer biology." (PMID 29682180, 2018). "However, the reduction or silencing of AGL activity has been observed to facilitate the growth of bladder tumor cells through various pathways." (PMID 38256214, 2024). "We have earlier shown that AGL is a regulator of bladder tumor growth." (PMID 29682180, 2018). "We further validate that AGL regulates NSCLC growth independent of its enzymatic function which is consistent with our previous findings in the bladder tumor model." (PMID 29682180, 2018).
Hypoglycemia (5 papers, 2022 to 2025). A decreased concentration of glucose in the blood. "Glycogen storage disease type III (GSD III) is a rare autosomal recessive glycogenolysis disorder due to AGL gene variants, characterized by hepatomegaly, fasting hypoglycemia, hyperlipidemia, elevated hepatic transaminases, growth retardation, progressive myopathy, and cardiomyopathy." (PMID 35578201, 2022). "GSD III (AGL, MIM# 232400), VI (PYGL, MIM# 232700) and IXα (PHKA2, MIM# 306000) belong to hepatic GSD with basic features of hepatomegaly and hypoglycemia." (PMID 36105079, 2022).
lung carcinoma (3 papers, 2020 to 2025). "This includes the glycogen debranching enzyme AGL which had a suppressing function in models of bladder and lung cancers, and the kinase PhK β-subunit (PHKB) which suppressed models of hepatocellular carcinoma." (PMID 33224887, 2020).
cardiomyopathy (2 papers, 2022 to 2023). A disease of the heart muscle or myocardium proper. "Cori–Forbes cardiomyopathy: this is a genetic disorder caused by mutations in the glycogen debranching enzyme (amylo-alpha-1, 6-glucosidase [AGL]) gene." (PMID 37685777, 2023).
carbohydrate metabolic disorder (1 paper, 2024). "ASL, AGL and GBE1 are among 135 genes revealed to be co-expressed in carbohydrate metabolic disorder." (PMID 38592052, 2024).
cryptogenic cirrhosis (1 paper, 2025). "Pathogenic variants were detected in the ABCB4 gene in a patient with idiopathic cholestasis, in the APOB and CP genes in a patient with hepatic steatosis, in the ABCB4 gene in a patient with elevated liver enzymes, and in the MTTP and AGL genes in a patient with cryptogenic cirrhosis." (PMID 40870862, 2025).
dysferlinopathy (1 paper, 2024). "Our profiling results indicate the downregulation of PYGM and AGL expression, suggesting impaired glycogen metabolism in dysferlinopathy." (PMID 39350328, 2024).
hypertriglyceridemia (1 paper, 2025). A laboratory test result indicating elevated triglyceride concentration in the blood. "Other rarer GSD subtypes causing hypertriglyceridemia: Also known as Cori or Forbes disease, GSD3 is an autosomal recessive disease caused by loss-of-function variants in the AGL gene." (PMID 40004987, 2025).
medulloblastoma (1 paper, 2024). A malignant, invasive embryonal neoplasm arising from the cerebellum. "CHEK2 and AGL require follow-up in future studies to determine their relationship with susceptibility to medulloblastoma." (PMID 39184053, 2024). "There were two genes (CHEK2 and AGL) that had P/LP variants enriched in medulloblastoma cases compared to controls that were not previously associated with medulloblastoma." (PMID 39184053, 2024). "AGL was the only AR gene that had P/LP variants enriched in cases compared to controls (p=0.035) and has not been previously associated with medulloblastoma." (PMID 39184053, 2024).
metabolic myopathy (1 paper, 2023). A group of rare inherited disorders characterized by a deficiency of enzymes that are involved in metabolic pathways that affect muscles. "They classified the AGL gene in the list of priority genes to be sequenced in cases of suspected metabolic myopathy." (PMID 37488624, 2023).
non-small cell lung carcinoma (1 paper, 2018). A group of at least three distinct histological types of lung cancer, including non-small cell squamous cell carcinoma, adenocarcinoma, and large cell carcinoma. "Here we investigate the role of AGL in non-small cell lung cancer." (PMID 29682180, 2018).
steatosis (1 paper, 2025). Increased lipid within the cytoplasm of cells. "AGL deficiency causes glycogen storage disease type III (GSD III), which is characterized by abnormal hepatic glycogen accumulation, steatosis, and progressive fibrosis." (PMID 41516281, 2025).
urothelial bladder cancer (1 paper, 2020). "Recently, the glycogen debranching enzyme amylo-α-1, 6-glucosidase, 4-α-glucanotransferase (AGL) was shown to have tumor suppressor functions in a model of urothelial bladder cancer." (PMID 31947882, 2020).
tumor (11 papers, 2016 to 2025). "It is believed that the overexpression of the enzymes SHMT2 and HAS2 with AGL loss drives increased synthesis of glycine and hyaluronic acid, leading to enhanced glucose absorption and metabolism that promotes rapid tumor proliferation and growth." (PMID 39858027, 2025). "Loss of AGL increased tumor growth in vitro and in xenografted tumors accompanied by an increase in abnormal glycogen structures (limit dextrin) and decrease in normal glycogen." (PMID 31947882, 2020). "Using genetic manipulation and chemical inhibition of HA synthesis we have demonstrated that HAS2 dependent HA synthesis is a major driven of tumor growth with AGL loss." (PMID 27595989, 2016). "Patients with low AGL tumor mRNA expression have poor survival outcomes, suggesting that low AGL expression promotes tumor growth after xenotransplantation." (PMID 38107059, 2023). "Accelerating glycogen metabolism can play a role in suppressing tumors, several enzymes involved in glycogen metabolism exert tumor-suppressive effects, including the glycogen debranching enzyme AGL and the kinase PhK β-subunit (PHKB)." (PMID 36425064, 2022). "Here for the first time we show that glycogen debranching enzyme (AGL) regulates NSCLC tumor growth." (PMID 29682180, 2018). "We also established that inhibition of glycogen breakdown in general, due to loss of AGL, does not promote tumor growth." (PMID 29682180, 2018). "The secondary objective was to lend credence to the hypothesis that AGL affects tumor biology by HAS2 mediated HA synthesis." (PMID 29682180, 2018). "We show that loss of AGL promoted rapid xenograft growth of H358, H2122 and A549 cells, however cells with and without AGL loss had similar tumor take." (PMID 29682180, 2018). "This established that AGL's known enzymatic functions do not play a role in tumor biology since both WT and the enzymatic null AGL rescued the increased growth phenotype seen with AGL loss." (PMID 29682180, 2018). "Currently mass spectrometric analysis is underway to decipher AGL-effector protein interactions to understand how loss of AGL might result in elevated HAS2 expression and aggressive tumor growth." (PMID 29682180, 2018). "The secondary objective was to lead credence to the hypothesis that AGL affects tumor biology by RHAMM downstream of HAS2/HA axis as well as other effectors such as SHMT2." (PMID 27595989, 2016). "Amylo‐alpha‐1‐6‐glucosidase‐4‐alpha‐glucanotransferase (AGL) may act as a tumor suppressor in BC." (PMID 38107059, 2023). "The results showed that AGL and SLC16A3 were significantly overexpressed in tumor samples compared to normal samples." (PMID 33991070, 2021). "The results showed that AGL, SLC16A3, and MIOX were significantly high expressed in tumor samples, whereas HKDC1 and ALDH7A1 were significantly low expressed in tumor samples." (PMID 33991070, 2021). "Even though HA has been previously shown to be a driver of growth and metastasis in various tumor models including NSCLC, here we show the importance of HA signaling in a subset of lung tumors which lack AGL expression." (PMID 29682180, 2018). "The AGL and ALDH3A2 were all significantly downregulated in the tumor tissues." (PMID 33391344, 2020). "By thorough experimentation we validated that AGL's enzymatic function does not play a role in regulating tumor growth." (PMID 29682180, 2018). "We have identified that AGL’s role in tumor biology is independent of its enzymatic activity and is not due to changes in glycogenolysis." (PMID 27595989, 2016). "However, studies had confirmed that the role of AGL in tumor biology was independent of its enzyme activity, rather than due to changes in glycogen decomposition." (PMID 33391344, 2020). "It is interesting to note here that the effect of the AGL in tumour growth was independent of its enzymatic activity, suggesting that AGL has an unknown non-enzymatic function." (PMID 26882899, 2016).
metabolic disorder (8 papers, 2016 to 2024). "In the current study, using WES technology, we have identified four different genetic variants in BTD, ASL, GBE1 and AGL in four Saudi families as an underlying cause of metabolic disorders." (PMID 38592052, 2024). "Interestingly, non-missense AGL mutations are overrepresented in the ISGSDIII cohort, whereas in most metabolic diseases missense mutations predominate." (PMID 27106217, 2016).
cancer (7 papers, 2016 to 2025). A tumor composed of atypical neoplastic, often pleomorphic cells that invade other tissues. "Darby Oldenburg had further identified that the loss of AGL promoted rapid cancer cell proliferation dependent on extracellular glucose." (PMID 33391344, 2020). "We further show that HAS2 driven HA synthesis and signaling via RHAMM is critical in regulating growth of these cancer cells with AGL loss." (PMID 29682180, 2018). "We have further identified that loss of AGL promotes rapid cancer cell proliferation dependent on extracellular glucose, Serine Hydroxymethyltransferase 2 (SHMT2) driven glycine synthesis and Hyaluronic Acid (HA) Synthase 2 (HAS2) mediated HA synthesis." (PMID 27595989, 2016). "Preclinical studies have shown that a subset of cancer cells, which have lost expression of the glycogen debranching enzyme (AGL) that cells use in metabolism, are highly sensitive to treatment with 4-MU." (PMID 38539529, 2024). "Increased levels of glycogen debranching enzyme (Q9UF08; AGL) in Ghost pepper treated cells appears to be an important characteristic of cancer cell pathophysiology." (PMID 30379886, 2018). "Cancer patients where AGL expression is low and HAS2 or RHAMM is overexpressed might be the best patient cohort who would responds to HA synthesis or signaling inhibitors." (PMID 29682180, 2018).
adenocarcinoma (1 paper, 2018). A common cancer characterized by the presence of malignant glandular cells. "We analyzed 4 independent patient cohorts of NSCLC adenocarcinoma patients with Stage I and II tumors (N = 555) to determine if AGL mRNA expression predicts patient outcome." (PMID 29682180, 2018).
inherited metabolic disorder (1 paper, 2024). "Moreover, functional enrichment analysis by STRING showed that BTD, ASL, GBE1 and AGL are among 726 genes co-expressed during inherited metabolic disorder." (PMID 38592052, 2024).
renal disease (1 paper, 2023). "We also identified 3 proteins, (Staphylococcal nuclease domain-containing protein 1 (SND1), glycogen debranching enzyme (AGL) and marginal zone B- and B1-cell-specific protein (MZB1) that were associated with the presence of active renal disease." (PMID 37516862, 2023).
AGL also shares sentences with these, for which no sentence is quoted: hyperlipidemia (3 papers); genetic disease (2); hepatocellular carcinoma (2); myopathy (2); bladder (1); cervical cancer (1); chronic pancreatitis (1); cutaneous melanoma (1); diabetes (1); Glycogen storage disease type VII (1); heart diseases (1); Hepatic steatosis (1); Hepatomegaly (1); infection (1); ischemic stroke (1); Leigh syndrome (1); leiomyosarcoma (1); liver disorder (1); lung adenocarcinoma (1); lysosomal storage disorder (1); McArdle disease (1); Niemann-Pick disease type A (1); Obesity (1); progressive familial intrahepatic cholestasis type 1 (1); prostate carcinoma (1); renal carcinoma (1); rhabdomyolysis (1); Stroke (1); Symbiosis (1).